IFNAR2-IL10RB (IFNAR2-IL10RB readthrough )
Gene: Protein-coding gene on chromosome 21 (33,229,892 to 33,297,160, forward strand). Ensembl gene ENSG00000249624.
Genetic constraint (gnomAD): Loss-of-function variants: 24 observed, 36.05 expected, observed/expected ratio (o/e) 0.67, 90% interval 0.48 to 0.94. Missense variants: 314 observed, 377.2 expected, observed/expected ratio (o/e) 0.83, 90% interval 0.76 to 0.91. Synonymous variants: 122 observed, 129.95 expected, observed/expected ratio (o/e) 0.94, 90% interval 0.81 to 1.09.